NFKBIZ (NFKB inhibitor zeta)
Diseases named in the same sentence as NFKBIZ in open-access papers (continued):
Sharing a sentence is not in itself a finding about the gene and the disease.
endothelial dysfunction (1 paper, 2025). In vascular diseases, endothelial dysfunction is a systemic pathological state of the endothelium (the inner lining of blood vessels) and can be broadly defined as an imbalance between vasodilating and vasoconstricting substances produced by (or acting on) the endothelium. "It was demonstrated that the genes associated with TNF-α signaling (TRAF1, TNFAIP2, and NFKBIZ) and oxidative stress regulation (SOD2) were significantly upregulated, suggesting that NS1 activates pathways critical for endothelial dysfunction and vascular inflammation." (PMID 40508120, 2025).
enteritis (1 paper, 2023). Inflammation of the small intestine. "Enteritis: IL-17 significantly promotes the expression of NFKBIZ in intestinal fibroblasts from Crohn’s disease (CD) patients." (PMID 37377955, 2023). "In addition, NFKBIZ upregulation has been reported in infection, kidney injury, enteritis, autoimmune disorders, metabolic diseases, and hypoxic damage." (PMID 37377955, 2023).
Hepatitis (1 paper, 2024). Inflammation of the liver. "Mechanistically, NFKBIZ downregulation can suppress the expression of IL-6 (a hepatoprotective cytokine) and resulted in restricted inhibition of hepatitis; NFKBIZ can also regulate triglyceride metabolism to attenuate the progression of nonalcoholic fatty liver disease." (PMID 38581570, 2024).
kidney cancer (1 paper, 2022). Primary or metastatic malignant neoplasm involving the kidney. "The overexpression of SIGIRR in RCC cells attenuated IL1-induced NFKBIZ activation, with a trend of effect on IL6, PD-L1, and ICAM1 induction, suggesting that SIGIRR manipulation may be beneficial to block IL1 in kidney cancer." (PMID 35814450, 2022).
mood disorder (1 paper, 2022). A cognitive disorder a disturbance in which the person's mood is hypothesized to be the main underlying feature. "We found a significant overlap for 6 hub genes (ADM, CITED2, IER5, NFKBIZ, SERTAD1, TNF) with similar co-expression and dysregulation patterns associated with mood disorder." (PMID 35386281, 2022).
nonalcoholic fatty liver disease (1 paper, 2024). "Previous researches have also indicated the intimate correlation between dysregulated expression of NFKBIZ and liver diseases such as acute hepatitis, nonalcoholic fatty liver disease and HBV- related HCC." (PMID 38581570, 2024).
psoriatic arthritis (1 paper, 2022). Joint inflammation associated with psoriasis. "Additionally, the rare genetic variant rs7152376 C in NFKBIZ was found to be more frequent in psoriatic arthritis patients in comparison to healthy controls." (PMID 36245291, 2022).
renal carcinoma (1 paper, 2022). A carcinoma arising from the epithelium of the renal parenchyma or the renal pelvis. "Our study shows that SIGIRR downregulation in RCC cells unleashes an inflammatory signaling intrinsic to renal cancer cells that leads to NFKBIZ activation, IL6 induction, MMP1 upregulation, and notably higher levels of PD-L1 and ICAM1 expression." (PMID 35814450, 2022).
respiratory failure (1 paper, 2023). The significant impairment of gas exchange within the lungs resulting in hypoxia, hypercarbia, or both, to the extent that organ tissue perfusion is severely compromised. "In our study, the haplotype combination of the polymorphisms in different NF-κB inhibitors genes (NFKBIA,NFKBIE and NFKBIZ) have been associated with respiratory failure, time to clinical stability and higher punctuations in the CURB-65 score." (PMID 38143267, 2023). "IL-R1 (rs3917267) and IL-10 (rs3024509) variants were related with respiratory failure (OR = 3.31, p = 0.001 and OR = 0.18, p = 0.003, respectively) as well as several haplotype combinations in NFKBIA, NFKBIZ, IL-R1 and IL-10 (p = 0,02, p = 0,01, p = 0,001, p = 0,03, respectively)." (PMID 38143267, 2023).
Salmonella Infections (1 paper, 2025). Infections with bacteria of the genus SALMONELLA. "Up regulation of hnRNPM after 4 hours of Salmonella infection stimulated the chemokine receptor CCRL2, the regulator of NF-κB (NFKBIZ) pathway." (PMID 41026719, 2025).
Sepsis (1 paper, 2020). Sepsis is defined as life-threatening organ dysfunction caused by a dysregulated host response to infection. "Essentially, NF-κB is activated in sepsis to repress miR-376b, leading to the expression of NFKBIZ, which conversely inhibits NF-κB and associated inflammation and tubular injury, providing an intrinsic protective mechanism." (PMID 33328388, 2020).
Streptococcus infections (1 paper, 2025). "NFKBIZ is strongly associated with Streptococcus infections in mastitis and is a potential genetic marker for mastitis resistance in dairy cattle." (PMID 40508044, 2025).
virus-infection (1 paper, 2025). "Contrastingly, numerous C/II and C/III members execute elevated/robust basal levels of expression and acquire an impulse of upregulation upon virus-infection (e.g. NFKBIZ), while a few establish minimal basal levels followed by slight upregulation e.g. TRIM69." (PMID 40131776, 2025).
tumor (19 papers, 2014 to 2026). "Reported solely in the context of skin inflammation is the TYK2-STAT3 requirement for expression of IκBζ (encoded by NFKBIZ); however, emerging reports suggest cell-intrinsic oncogenic, as well as tumor-suppressive, functions of IκBζ." (PMID 31694222, 2019). "Of the cases with sufficient depth and at least one heterozygous SNP in NFKBIZ, 24 SNPs in 18 tumours exhibited significant AI favouring the mutant allele." (PMID 30275490, 2018). "Additionally, we focused on the EMT, a process intricately associated with tumor metastasis, and demonstrated that NFKBIZ could inhibit this process to impede HCC progression." (PMID 38581570, 2024). "NFKBIZ, a member of the nuclear factor kappa B inhibitory family, is closely related to tumor progression." (PMID 38581570, 2024). "In either case, multicenter trails are warranted to validate the impacts of NFKBIZ on tumor metastasis in the real world." (PMID 38581570, 2024). "We show that NFKBIZ mRNA is low to undetectable in unstimulated tumor cells while it is induced by IL1β in two different ccRCC cell lines, although it was not increased in a dose-dependent manner." (PMID 35814450, 2022). "Seven tumor antigens (ADA, FYN, HDC, NFKBIZ, RASSF4, SLC6A3, and UPP1) associated with inferior prognoses and higher-level infiltration of antigen-presenting cells in PRAD were identified, thus promising candidates for mRNA vaccine." (PMID 35547260, 2022). "While, the paired analysis showed that expression of IL26, IL17F, KLRB1, CD40LG, JCHAIN, and NFKBIZ were significantly lower in the tumor group, compared with normal tissues." (PMID 35902909, 2022). "Consequently, downstream targets of NFκB that promoted tumor progression were downregulated due to NFKBIZ overexpression." (PMID 38581570, 2024). "Taken together, we uncovered that HCC cells may develop insensitivity to the anti-tumor drug sorafenib by an increased degradation of NFKBIZ through ubiquitination." (PMID 38581570, 2024). "To explore the underlying mechanisms that NFKBIZ affected HCC migration and invasion, we investigated the correlation between NFKBIZ and epithelial-mesenchymal transition (EMT), which is closely linked to tumor metastasis and invasion." (PMID 38581570, 2024). "Furthermore, future studies should further elucidate the molecular basis of this novel NFKBIZ tumor suppression in the setting of CAC." (PMID 37884500, 2023). "In addition, genes that were upregulated in tumor-derived iCAFs were associated with the regulation of the inflammatory response, namely, IL6ST, NFKBIA, NT5E, SERPINF1, and NFKBIZ, suggesting that they play roles in communicating with immune cells." (PMID 34976204, 2022). "The upregulated expression of the FLT3, MEF2C, NFKBIZ, and MDM2 genes in sarcoid AMs suggests the potential side effect of DEX and it may lead to increased risk of tumor cell proliferation." (PMID 32477331, 2020). "Several of the genes differentially regulated are associated with tumor initiation (e.g., AhR, CYP1A1, CYP1A2, MDM2, EGR1, NFKBIZ), further suggesting that genomic outcomes of short-term exposure truly reflect the longer-term process of malignant transformation." (PMID 25058030, 2014). "Clinical character analysis indicated that NFKBIZ high expression was significantly related to reduced HCC recurrence rate, lower HBV infection rate and decreased tumor size." (PMID 38581570, 2024). "To further verify the effect of NFKBIZ on tumor formation in vivo, we constructed the xenograft mouse model by subcutaneously injecting MHCC97H and Huh7 with stable Vector expression and NFKBIZ overexpression into the left and right back of nude mice, respectively." (PMID 38581570, 2024).
tumor (continued). "NK_c3 and NK_c5 were mainly derived from non-tumor liver tissues (23.57% and 5.97%, respectively) and characterized by high expression of transcription factors such as FOS, FOSB, FOXP1, and ATF4, and two genes involved in the NF-κB pathway, NFKBIA and NFKBIZ." (PMID 33298893, 2020). "Indeed, mice with NFKBIZ conditionally deleted in the colon were protected against tumors induced by AOM/DSS, rather than advancing tumor burden." (PMID 37884500, 2023).
infection (13 papers, 2020 to 2026). The state of being infected such as from the introduction of a foreign agent such as serum, vaccine, antigenic substance or organism. "NFKBIZ expression was increased in porcine alveolar macrophage (PAM) infection and porcine reproductive and respiratory syndrome virus (PRRSV) infection." (PMID 37377955, 2023). "Regulation of CXCR4, DDX60 and NFKBIZ varied at different time points after infection of chicken lungs." (PMID 32381003, 2020). "Remarkably, our follow-up data revealed that HCC patients with high NFKBIZ expression exhibited lower infection rate of HBV, and this may be a clue to support our speculation." (PMID 38581570, 2024). "Additionally, we identified 10 genomic regions associated with breakthrough infection (SLC6A20, ST6GAL1, MUC16, FUT6, MXI1, MUC4, HMGN2P18-KRTCAP2, NFKBIZ and APOC1), and one with breakthrough severity (APOE)." (PMID 39384777, 2024). "In addition to the cytokine and chemokine upregulation observed in this present work, the inflammatory response regulators SLAMF7, RELB, NFKBIZ, NFKBIA, and ZC3H12A were identified, further underlining the strong inflammatory response elicited by PCPEC during to infection." (PMID 33763387, 2021). "Pathways involved in chemokine receptor signaling were also significantly enriched, highlighting the recruitment of immune cells to the site of infection (NFKBIA, NFKBIB, NFKBIE, NFKBIZ, TNFAIP3, REL, BCL3)." (PMID 40634947, 2025). "Our RNA-seq analysis shows that several inhibitors of the NF-kB and MAPK signaling pathways were significantly down-regulated 36 days after infection, including NFKBID, NFKBIZ, DUSP-1, -2, NR4A2, and tristetraprolin (TTP or ZFP36)." (PMID 33324683, 2020). "This was supported by the upregulation of the NF-kB inhibitor genes NFKBIA and NFKBIZ, the AP-1 transcription factor complex genes FOS, JUN, FOSB and JUNB as well as other NF-kB target genes such as TNFAIP3, RELB, NR4A2, DUSP1 and CD69 in response to infection." (PMID 37700317, 2023). "Meanwhile, anti-inflammatory factors such as TNFAIP3, NFKBIA, NFKBIZ, SOCS1, SOCS3, and IL-10 were elevated, with the reverse trends for the inflammation-inducing genes PPBP and MARCO at 38 hpi, suggesting that the pro- and anti-inflammatory responses might coexist in PAMs during YC-2020 infection." (PMID 36338035, 2022).
cancer (11 papers, 2016 to 2025). A tumor composed of atypical neoplastic, often pleomorphic cells that invade other tissues. "Further, an upregulation of CXCR4, the receptor of the cytokine CXCL12 (known to exclude T-cells in cancer) was linked to increased CXCL12 and a downregulation of NF-kappa-B inhibitor zeta (NFKBIZ) in fibroblast foci." (PMID 38012580, 2023). "Since literature evidence supports the important roles of CD44, BATF, LGALS3, and NFKBIZ in cancer, we decided to validate the expression of these genes with independent experimental methods." (PMID 36982699, 2023). "An intestinal immune network for IgA production might provide new markers in enteric DLBCL, such as CCR10, TNFRSF13B, AICDA, and HLA-DOB, as well as genes involved in transcriptional misregulation in cancer (NFKBIZ, FUT8, LMO2, CCND2, BCL2A1, ETV6, and CDK14)." (PMID 29992138, 2018).
bacterial infection (1 paper, 2025). "NFKBIZ is another key marker identified in this study which might play a major role in responding to bacterial infection." (PMID 40581066, 2025). "Other monocyte informative genes were also activated in patients with bacterial infection including NLRC4, CYP1B1, PFKFB3, LILRA5, NFKBIA, and NFKBIZ." (PMID 40581066, 2025). "In this article, we shortlisted activated target genes in monocytes during acute bacterial infection, including VNN1, NLRC4, CYP1B1, PFKFB3, LILRA5, NFKBIA or NFKBIZ." (PMID 40581066, 2025).
kidney disease (1 paper, 2023). "Other studies have indicated that HBB, HSPA6, and NFKBIZ may play essential roles in kidney disease." (PMID 37293297, 2023).
NFKBIZ also shares sentences with these, for which no sentence is quoted: epilepsy (3 papers); colorectal tumors (2); hepatocellular carcinoma (2); neuropathy (2); adenoma (1); Arrhythmia (1); atopic dermatitis (1); autoimmune disease (1); breast carcinoma (1); Chronic colitis (1); chronic myeloid leukemia (1); colon adenocarcinoma (1); cystic fibrosis (1); familial hemiplegic migraine type 3 (1); glioma (1); infarction (1); liver fibrosis (1); melanoma (1); membranous nephropathy (1); metastatic disease (1); ovarian carcinoma (1); prostate carcinoma (1); renal fibrosis (1); tendinopathy (1); type 2 diabetes (1).